TINCR (TINCR ubiquitin domain containing)
Diseases named in the same sentence as TINCR in open-access papers (continued):
Sharing a sentence is not in itself a finding about the gene and the disease.
colon cancer (2 papers, 2023). "The present study aimed to evaluate the effects of long noncoding (lnc)RNA TINCR ubiquitin domain containing (TINCR) on the development of colon cancer, and the specific underlying mechanisms." (PMID 37051356, 2023). "In addition, the results of the present study demonstrated that lncRNA TINCR was associated with clinicopathology in patients with colon cancer." (PMID 37051356, 2023). "Moreover, the effects of TINCR knockdown on the bioactivity of colon cancer cells and the underlying molecular mechanisms were explored using in vitro cell experiments." (PMID 37051356, 2023). "In addition, the association between TINCR expression and the pathology and prognosis of patients with colon cancer was investigated using in situ hybridization and reverse transcription‐quantitative (RT‐q) PCR." (PMID 37051356, 2023). "Notably, the results of the present study demonstrated that lncRNA TINCR knockdown exhibited antitumor effects to reduce mTOR gene and protein expression, and this may be associated with autophagy in colon cancer." (PMID 37051356, 2023). "Results of the present study demonstrated that lncRNA TINCR expression was significantly upregulated in colon cancer tissues, and the overall survival of the low‐expression group was significantly increased, compared with that of the high‐expression groups." (PMID 37051356, 2023). "Abnormally high‐expression levels of lncRNA TINCR play an important role in the tumorigenesis and progression of colon cancer." (PMID 37051356, 2023). "Results of the present study demonstrated that TINCR knockdown impacted the biological activities of colon cancer cells." (PMID 37051356, 2023). "Results of the present study demonstrated that the expression levels of lncRNA TINCR in colon cancer tissues are higher than those in ANTs, indicating that lncRNA TINCR may play a role in promoting cancer." (PMID 37051356, 2023). "Moreover, the results of the present study demonstrated that lncRNA TINCR is overexpressed in colon cancer cell lines." (PMID 37051356, 2023). "Thus, the expression levels of TINCR were investigated in colon cancer tissues and ANTs in the present study." (PMID 37051356, 2023). "Collectively, these results demonstrated that lncRNA TINCR may induce colon cancer development through the regulation of autophagy." (PMID 37051356, 2023). "However, the effects of TINCR on colon cancer remain to be fully elucidated." (PMID 37051356, 2023). "Moreover, lncRNA TINCR knockdown may effectively inhibit the tumorigenesis and progression of colon cancer." (PMID 37051356, 2023). "lncRNA TINCR could induce colon cancer development by regulating autophagy." (PMID 37051356, 2023). "In addition, following lncRNA TINCR knockdown in vitro, results of the present study demonstrated that the bioactivity (proliferation, invasion, and migration) of HT‐29 and SW620 cells was significantly inhibited, indicating that TINCR may play a promoting role in the progression of colon cancer." (PMID 37051356, 2023). "Thus, we hypothesized that lncRNA TINCR may be an oncogenic gene in colon cancer." (PMID 37051356, 2023). "Results of the present study demonstrated that when compared with ANTs, the expression levels of lncRNA TINCR were significantly elevated in tissues obtained from patients with stage I–II and III–IV colon cancer (p < 0.01)." (PMID 37051356, 2023). "Further clinical analysis demonstrated that the expression of lncRNA TINCR in stage M1 patients is higher than that in stage M0 patients and that its expression level in patients with stage III–IV colon cancer is also higher than that in patients with stage I–II colon cancer." (PMID 37051356, 2023).
cutaneous squamous cell carcinoma (2 papers, 2020 to 2023). "To further explore the impact of TINCR inactivation in human cancer we performed immunohistochemical analysis across two independent cohorts of cutaneous squamous cell carcinoma (cSCC) samples encompassing a total of 141 patient samples (HUCA n = 100; cSCC SK801c n = 41)." (PMID 36899004, 2023).
psoriasis (2 papers, 2022 to 2025). An autoimmune condition characterized by red, well-delineated plaques with silvery scales that are usually on the extensor surfaces and scalp. "Notable representation is also observed in psoriasis and autoimmune diseases, particularly through lncRNAs such as TINCR, MALAT1, and NORAD, as well as miRNAs like miR-17-5p, miR-26b-5p, and let-7i-5p." (PMID 40725409, 2025). "When evaluating gene expression patterns in lesional compared to control skin, DANCR was upregulated and TINCR was downregulated in psoriasis lesional skin." (PMID 35559048, 2022). "While TINCR is known to play a role in keratinocyte differentiation, its dysregulation in atopic dermatitis and psoriasis has not yet been fully understood." (PMID 35559048, 2022).
atopic dermatitis (1 paper, 2022). "Of importance, we discovered that TINCR was also downregulated in atopic dermatitis lesional skin—a finding that has not previously been reported." (PMID 35559048, 2022).
bladder urothelial carcinoma (1 paper, 2016). "Silencing TINCR expression inhibited cell proliferation and promoted apoptosis in vitro, indicating that TINCR may be the potential therapeutic target for treating bladder urothelial carcinoma." (PMID 27586866, 2016).
breast tumor (1 paper, 2018). "Taken together, our data demonstrated that TINCR apparently involved in the metastatic process during breast tumor progression." (PMID 29614984, 2018). "We also evaluated the potential contribution of TINCR to breast tumor metastasis." (PMID 29614984, 2018).
cutaneous melanoma (1 paper, 2023). A primary melanoma arising from atypical melanocytes in the skin. "Furthermore, a 2021 in vitro and in vivo study investigated the role of lncRNA TINCR ubiquitin domain containing (TINCR) in cutaneous melanoma." (PMID 37629553, 2023).
laryngeal carcinoma (1 paper, 2021). Carcinoma that arises from the laryngeal epithelium. "We also observed the abolished expression of Ki67, suggesting that TINCR plays an essential role in the proliferation of laryngeal cancer cells." (PMID 34187411, 2021). "The results suggested that the invasion and proliferation of laryngeal carcinoma cells with high TINCR expression were lower than those of TU212 cells with low TINCR expression." (PMID 34187411, 2021). "The results suggested that TINCR overexpression significantly inhibited the migration of TU212 laryngeal cancer cells." (PMID 34187411, 2021). "Therefore, this study aims to determine the role of TINCR in the development of laryngeal carcinoma and explore its interaction with other miRNAs to elucidate the underlying mechanism." (PMID 34187411, 2021). "In addition to verifying TINCR function in vitro, we also established a laryngeal cancer xenograft model to investigate its effects in vivo." (PMID 34187411, 2021). "However, for the study of TINCR in laryngeal cancer, we only focused on miRNAs and did not determine its binding effect on proteins, which will be an important direction for further study of TINCR." (PMID 34187411, 2021).
laryngeal squamous cell carcinoma (1 paper, 2021). A squamous cell carcinoma that arises from the larynx. "We used qRT-PCR to detect the expression of TINCR in laryngeal squamous cell carcinoma (LSCC) tissues and cells and found significantly lower levels in cancer tissues compared with adjacent tissues." (PMID 34187411, 2021). "qPCR was used to detect the expression level of TINCR in tissues and cell lines of laryngeal squamous cell carcinoma (LSCC)." (PMID 34187411, 2021).
metastatic disease (1 paper, 2023). "Finally, extended analysis of homogeneously treated and clinically annotated tumor cohorts will be instrumental in better defining the association of loss of TINCR protein expression with aggressive poorly differentiated tumor histopathology, metastatic disease, and outcomes." (PMID 36899004, 2023).
oropharyngeal squamous cell carcinomas (1 paper, 2023). "Consistently, fluorescence in situ hybridization analysis of the TINCR gene showed ~27% heterozygous deletions and 7% homozygous loss in an independent series of oropharyngeal squamous cell carcinomas (n = 156)." (PMID 36899004, 2023).
tumor (44 papers, 2016 to 2025). "LncRNAs such as GATA3-AS1 and TINCR have been implicated in tumor progression, immune evasion and resistance to PD-L1 inhibitors." (PMID 39188717, 2024). "And the average weight of TINCR-deficient xenograft tumor was 0.5 g compared to 1.3 g in control mice." (PMID 29614984, 2018). "After tumor tissues were classified into two subgroups (high-TINCR expression subgroup and low-TINCR expression subgroup), the association of TINCR expression level with clinicopathological characteristics of HCC patients were further analyzed." (PMID 28546230, 2017). "Collectively, these results indicate that loss of TINCR expression profoundly promotes tumour growth and metastasis." (PMID 27009809, 2016). "Furthermore, the terminal differentiation-induced Non-Coding RNA (TINCR) encodes a highly conserved ubiquitin-like microprotein that serves as a tumor suppressor to repress tumor growth of squamous cell carcinoma." (PMID 39443468, 2024). "Similarly, loss of TINCR protein was detected in over 30% of patient samples from an HNSCC cohort (HUCA n = 306) across all tumor differentiation grades." (PMID 36899004, 2023). "Finally, genetic analyses identify loss-of-function mutations and deletions encompassing the TINCR gene in SCC clinical samples supporting a tumor suppressor role in human cancer." (PMID 36899004, 2023). "In view of the role of TINCR in carcinogenesis and tumor formation, we proposed the hypothesis that single nucleotide polymorphisms (SNPs) in the lncRNA TINCR may affect genetic susceptibility to GC." (PMID 27893425, 2016). "This TINCR–miR-199a–USP20 axis contributes to tumor resistance to T cell killing, whose effects can be reversed by either TINCR knockdown and/or PD-L1 blockade effects." (PMID 41154428, 2025). "Compared with the scramble group, tumor growth was significantly inhibited in the TINCR knockdown groups." (PMID 36725842, 2023). "Mechanistically, ZNF750 has been reported to mediate tumor-suppressive roles by regulating the expression of various downstream genes, such as TINCR, LAMC2, DANCR, FGF14, and SNAI1." (PMID 37365152, 2023). "Low expression of TINCR significantly inhibited tumor volume and weight in vivo, and had the same inhibitory effect on cell proliferation, as well as reducing the aggressiveness of tumor cells." (PMID 37901333, 2023). "Our findings suggest that IFN-γ promotes tumor immune escape by transcriptionally activating TINCR via STAT1, which in turn upregulates PD-L1 expression." (PMID 36725842, 2023). "Furtherly, liver orthotopic tumors model was established to show that TINCR knockdown exhibited decreased tumor size and lower fluorescence intensities." (PMID 36385098, 2022). "Synchronously, ST6GAL1 expression in tumor tissues was reduced with the silencing of TINCR (P < 0.05)." (PMID 34980201, 2022). "TINCR lncRNA has been documented to be deregulated in various tumor types, and its role as an oncogene or as a tumor-suppressor seems to be tumor specific." (PMID 36369429, 2022). "The mouse xenograft experiment further verified that knockdown TINCR attenuated tumor progression and oxaliplatin resistance in vivo." (PMID 34980201, 2022). "In vivo, different dilutions of stable knockdown of TINCR and shCtrl HCC primary cells were used to investigate the role of TINCR in tumor-initiating formation." (PMID 36385098, 2022). "During the monitoring of tumor growth, TINCR depletion resulted in significantly decreased tumor growth and smaller final tumor size." (PMID 36385098, 2022). "qRT-PCR analysis also revealed that tumor tissues in the sh-TINCR group expressed lower TINCR levels than those of the control group." (PMID 33649294, 2021).
tumor (continued). "In order to further evaluate the tumor-promoting effect of TINCR in vivo, a xenograft tumor model was constructed." (PMID 33649294, 2021). "The survival rate of tumour-bearing mice overexpressing TINCR was significantly higher than that of control mice (P < 0.05)." (PMID 34187411, 2021). "Upregulation of TINCR significantly elevated the expression of terminal differentiation genes and repressed tumor growth in vivo." (PMID 33732637, 2021). "Further experiments with tumour-bearing nude mice showed that TINCR upregulation inhibited tumour growth." (PMID 34187411, 2021). "Additional results showed that the expression of Ki67 was significantly lower in the TINCR-overexpressing group compared with the control group, indicating that tumour cell proliferation was inhibited." (PMID 34187411, 2021). "In GC, upregulated E2F1 expression, targeting the TINCR/STAU1/CDKN2B signaling axis, was positively associated with poor prognosis due to its association with advanced stage and larger tumor size." (PMID 34532281, 2021). "In this context, it is interesting that ZNF750 which upregulates the expression of TINCR in keratinocytes, was recently shown to exert a tumor-suppressive role in SCCs of head and neck, lung, cervix, and skin." (PMID 32462404, 2020). "The increase in TINCR expression inhibited Caco-2 tumor cell growth in vivo, shown by quantification (p<0.05), and by representative images." (PMID 32681722, 2020). "In summary, our study showed that TINCR is an endogenous sponge of miR-31, while the decrease in TINCR expression increases the miR-31 expression, thereby enhancing tumor growth in CRC." (PMID 32681722, 2020). "This means that TINCR exert oncogenic effects in some human tissues and tumor suppressive effects in others." (PMID 32695943, 2020). "Of note, a number of lncRNAs with broad oncogenic (SNHG12, CASC9, LUCAT1 and PVT1) or tumor suppressor (such as TINCR) function were also identified to be differentially expressed in cSCC25–28." (PMID 32108138, 2020). "TINCR depletion increased tumor growth in vivo, while TINCR overexpression inhibited tumor growth in vivo." (PMID 32681722, 2020). "We also observed that TINCR, acting as a miR-7-5p sponge, promoted tumor growth, migration, invasion and metastasis in CRC." (PMID 30853664, 2019). "TINCR silencing significantly suppressed migration and invasion in vitro and xenograft tumor growth in vivo." (PMID 29614984, 2018). "The continuous inspection observed significant delay in tumor growth in TINCR-knockdown mice compared to the control." (PMID 29614984, 2018). "The representative images of macroscopic xenograft tumor extracted from sacrificed mice revealed much smaller size in TINCR knockdown group." (PMID 29614984, 2018). "We verified the persistent knockdown of TINCR in our xenograft tumor model at the endpoint of our experiment." (PMID 29614984, 2018). "More recently, the potential roles of TINCR in tumor biology have been cumulatively uncovered in variety of human malignances." (PMID 29614984, 2018). "To exclude the potential artifacts associated with cell culture, we further investigated the impact on tumor growth of TINCR inhibition in xenograft tumor model." (PMID 29614984, 2018). "Results revealed that high TINCR expression was significantly correlated with tumor size (P=0.005), tumor differentiation status (P=0.017), TNM stage (P=0.010), and vascular invasion (P=0.004)." (PMID 28546230, 2017). "Compared with normal adjacent gastric epithelium tissues, TINCR expression levels were aberrantly up-regulated in GC tissues, indicating a novel mechanism for TINCR in tumor development." (PMID 27893425, 2016). "We next examined the relationship between TINCR expression levels and the clinicopathological characteristics of the tumour tissue samples." (PMID 27009809, 2016).